RNU6-447P (RNA, U6 small nuclear 447, pseudogene)
Gene: Small nuclear RNA gene on chromosome 11 (152,999 to 153,102, reverse strand). Ensembl gene ENSG00000222225.
Homologues: Orthologues: chimpanzee U6 (100% identical), macaque U6 (91% identical), pig U6 (84% identical), pig U6 (78% identical), dog U6 (77% identical). Paralogues in human: RNU6-1076P (100% identical), RNU6-1100P (100% identical), RNU6-1118P (100% identical), RNU6-1217P (100% identical), RNU6-355P (100% identical), RNU6-785P (100% identical), RNU6-791P (100% identical), RNU6-860P (100% identical), U6 (100% identical), RNU6-1054P (99% identical), RNU6-1199P (99% identical), RNU6-1319P (99% identical), and 1289 more.